HDAC2 (histone deacetylase 2)
Diseases named in the same sentence as HDAC2 in open-access papers (continued):
Sharing a sentence is not in itself a finding about the gene and the disease.
cardiac hypertrophy (continued). "ISP failed to induce cardiac hypertrophy in the TgPPP2CA mouse heart, whereas significant cardiac hypertrophy was induced by adenoviral HDAC2 S394E." (PMID 30050113, 2018). "Because PPP2CA blocked the hypertrophic stress-induced phosphorylation and activation of HDAC2, we concluded that PPP2CA functions as a phosphatase in association with cardiac hypertrophy." (PMID 30050113, 2018). "Like the WT HDAC2, HDAC2 S394E, a constitutively active form of HDAC2 also induced cardiac hypertrophy (b 5th column)." (PMID 30050113, 2018). "Vice versa, cardiac-specific overexpression of HDAC2 resulted in cardiac hypertrophy, indicating that HDAC2 is not only required but also sufficient to drive maladaptive cardiac remodeling." (PMID 24310814, 2014). "Further, studies demonstrated that Trichostatin-A (TSA), a HDAC2 inhibitor, attenuated the development of cardiac hypertrophy." (PMID 25380525, 2014). "In order to test the role of Jak2 and HDAC2 in cardiac hypertrophy response, siRNA strategy was utilized to selectively knockdown Jak2 or HDAC2 in H9c2 cardiomyocytes." (PMID 25380525, 2014). "Significantly, we found that AB-induced HDAC2 nuclear exportation in hearts, which was almost blocked by Jak2 inhibitor AG-490, the latter also prevented cardiac hypertrophy." (PMID 25380525, 2014). "HDAC1 and HDAC2 regulate cardiac hypertrophy in a similar manner, and HDAC1 deficiency induces HDAC2 expression in embryonic stem cells." (PMID 23835259, 2013). "In vivo, class I HDAC2 overexpressing transgenic animals develop cardiac hypertrophy whereas HDAC2-null animals are protected from cardiac hypertrophic response after stimulation either by pressure overload or isoproteranol (ISO) administration." (PMID 24198825, 2013). "Cardiac specific loss of HDAC1 and HDAC2 for example results in cardiac arrhythmias and heart failure, while loss of HDAC3 function leads to cardiac hypertrophy." (PMID 23341106, 2013). "HDAC2 knockdown increases H3K4me3‐directed Kv channel‐interacting protein 2 (KChIP2) expression through CNOT4‐mediated KDM5 degradation to alleviate ventricular arrhythmias during cardiac hypertrophy." (PMID 40497340, 2025). "HDAC2 may be involved in the pathogenesis of cardiac hypertrophy via modulation of the PI3K, Akt and GSK3β signalling pathway." (PMID 40497340, 2025). "Collectively, these results suggest that HSP70 may contribute to Asb10 overexpression induced cardiac hypertrophy by increasing cardiac inflammation and phosphorylation of HDAC2." (PMID 40399264, 2025). "HDAC2 is a major regulator of the nuclear distribution of cardiac hypertrophy." (PMID 40497340, 2025). "In addition to cardiac inflammation, HSP70-mediated phosphorylation of the S394 site of HDAC2 was reported to contribute to the development of cardiac hypertrophy." (PMID 40399264, 2025). "Eom and colleagues examined HDAC2's role in cardiac hypertrophy using transgenic mice." (PMID 40660005, 2025). "Additionally, Hsp70 is involved in the development of cardiac hypertrophy via the Akt pathway by interacting with HDAC2, which plays a direct role in this process." (PMID 40497340, 2025). "Cardiomyocyte-specific transgenic OE of HDAC2 with αMHC promoter resulted in cardiac hypertrophy." (PMID 38983721, 2024). "In addition, Hdac2 knockout mice were resistant to undesirable stimuli that induce cardiac hypertrophy, such as pressure overload and calcineurin stimulation." (PMID 35958418, 2022). "HDAC2 selective inhibitor magnesium valproate has been reported to attenuate cardiac hypertrophy." (PMID 33959033, 2021). "Among Class I HDACs, HDAC2 has been reported to play a key role in cardiac hypertrophy; however, the exact function of HDAC8 remains unknown." (PMID 33959033, 2021). "For example, it has been shown that Hdac2 over-expression provokes severe cardiac hypertrophy." (PMID 25268775, 2014). "It has also been suggested that HDAC2 is an important player in cardiac hypertrophy." (PMID 25380525, 2014).
cardiac hypertrophy (continued). "Further, the reduction in HDAC2 protein levels in db mouse hearts did not occur until 4 weeks, and was associated with overt cardiac hypertrophy." (PMID 23835259, 2013). "Although HDAC2 and HDAC8 promote cardiac hypertrophy, the underlying mechanisms may vary." (PMID 35126818, 2022). "Furthermore, the phosphorylation of HDAC2 by casein kinase 2α1 is required for cardiac hypertrophy." (PMID 33959033, 2021). "Importantly, enzymatic activation of HDAC2 preceded the hypertrophic events, implying that activation of HDAC2 is the cause of cardiac hypertrophy and not a consequence." (PMID 32733053, 2020). "Because HDAC2 is activated by a series of posttranslational modifications during the development of cardiac hypertrophy, the inactivation of HDAC2 could be used as a mechanism to inhibit cardiac hypertrophy." (PMID 30050113, 2018). "Thus, HDAC2 is considered as an important signaling molecule for cardiac hypertrophy." (PMID 25380525, 2014). "Class I HDACs (HDAC1, HDAC2, HDAC3, and HDAC8) are considered as pro‐hypertrophic factors and opposing regulators of cardiac hypertrophy, where their inhibition confers protection against the incited hypertrophic response." (PMID 39690876, 2025). "An elevated expression of p‐HDAC2, and its downstream proteins p‐AKT and p‐GSK3β, was found in ISP‐induced cardiac hypertrophy in both in vitro and in vivo models." (PMID 39690876, 2025). "In summary, HDACs, especially those from class I such as HDAC1, HDAC2, and HDAC8, are key players in the promotion of cardiac hypertrophy through the activation of prohypertrophic signalling pathways and the repression of protective genes." (PMID 40660005, 2025). "Treatment of mice overexpressing Hdac2 with TSA increases GSK3β and following INPP5f activity, which prevents cardiac hypertrophy." (PMID 35958418, 2022). "The role of HDAC2, which is the best characterized HDAC, in cardiac hypertrophy has been previously reported." (PMID 35126818, 2022). "Unlike Hdac2-Tg mice, Hdac3-Tg mice do not exhibit cardiac hypertrophy, which indicates that Hdac3 is a unique regulator of cardiac cell proliferation." (PMID 40660005, 2025). "Other studies have shown that plantamajoside, an extract of Plantaginis Herba, can inhibit the activation of histone deacetylase 2 (HDAC2), and the transduction of downstream signals, AKT/GSK-3β, in turn has an important protective effect against cardiac hypertrophy." (PMID 33897800, 2021). "The dominant negative mutant of cardiac HDAC2 inhibited AB-induced cardiac hypertrophy response, indicating a critical role HDAC2 in the process." (PMID 25380525, 2014). "For example, the enzymatic activity but not the expression of HDAC2 promotes cardiac hypertrophy." (PMID 35126818, 2022).
lung carcinoma (37 papers, 2012 to 2026). "Histone deacetylase 2 can regulate the expression of eIF5 in lung cancer, and its high expression is associated with a poorer prognosis in lung cancer patients." (PMID 36360287, 2022). "Silencing of HDAC2 enhanced the cell death caused by ionizing radiation in lung cancer cells." (PMID 25605253, 2015). "In lung cancer, intratumoral butyrate-producing bacteria, such as Roseburia, epigenetically up-regulate H19 via histone deacetylase 2 (HDAC2) inhibition, thereby driving M2 polarization and promoting recurrence." (PMID 41355895, 2025). "The downregulation of HDAC2 induced the expression of E3 ubiquitin-protein ligase c-Cbl in lung cancer cells." (PMID 36968022, 2023). "Overexpression of HDAC2 promotes lung cancer cell migration, whereas shHDAC2 effectively inhibits it." (PMID 37495623, 2023). "CBX7, for example, shows an antitumor activity in lung cancer through interacting with histone deacetylase 2 (HDAC2) and inhibiting CCNE1 expression." (PMID 37691307, 2023). "The present study has demonstrated that both trichostatin A (TSA) and sodium butyrate (NaBu) significantly inhibit the invasion and migration of lung cancer cells via Histone deacetylase 2 (HDAC2)." (PMID 37495623, 2023). "In order to examine the potential impact of HDAC2 on the survival of individuals with lung cancer, an analysis of the TCGA database was conducted utilizing GEPAI." (PMID 37495623, 2023). "Abnormal expression of histone deacetylases (HDACs) is often reported in various types of cancers, e.g., overexpression of HDAC1-3 in ovarian cancer, overexpression of HDAC 1 and 3 in lung cancer and overexpression of HDAC2 in gastric cancer." (PMID 37101287, 2023). "Halofuginone also inhibits exosome secretion from lung cancer cells and downregulates histone deacetylase 2 (HDAC2), which stalls cell cycle transition." (PMID 35706397, 2022). "In NSCLC, HDAC2 knock down correlates with a low expression of fibronectin (FN) and enhances the metastatic potential of lung cancer cells." (PMID 36142846, 2022). "In leukemia, HDAC2 silencing induces modulation of gene expression leading to strong transcriptional activation while in lung cancer, HDAC2 has been proposed to exert an effect on survival by sustaining Mdm2-survivin levels." (PMID 26683361, 2016). "Clinically, the mRNA levels of HDAC2 and survivin were prominently overexpressed in lung cancer patients compared to normal lung tissues." (PMID 25605253, 2015). "In lung cancer patients, survivin and HDAC2 mRNA expression were overexpressed compared to normal lung tissues." (PMID 25605253, 2015). "Endogenous HDAC2 directly correlates with BAP1 across a panel of lung cancer cell lines, and is downregulated in mesothelioma cell lines with genetic BAP1 inactivation." (PMID 25970771, 2015). "We report here an unbiased DUB siRNA screen that has identified BAP1 as a regulator of HDAC2 expression in lung cancer and mesothelioma cells." (PMID 25970771, 2015). "Our data show coordinated transcription of HDAC1 and HDAC2 in lung cancer cell lines, but suggest HDAC2 protein expression is cell-context specific." (PMID 25970771, 2015).
lung carcinoma (continued). "Survivin expression levels in lung cancer cell lines were highly correlated with HDAC2 expression levels." (PMID 25605253, 2015). "Moreover, myeloid cell-specific deletion of Hdac2 and pharmacologic inhibition of all class I HDACs in four different murine lung cancer models induced the switch from M2-type to M1-type TAMs." (PMID 40375990, 2025). "In lung cancer, butyrate-producing microbial communities were found to upregulate genes related to H19, a long non-coding RNA (lncRNA), by inhibiting histone deacetylase 2 (HDAC2), thereby promoting histone H3 lysine 27 acetylation (H3K27 acetylation) and enhancing H19 promoter activity." (PMID 39921821, 2025). "Suppression of HDAC2 in TAMs suppressed their protumoral secretome, while the spatial proximity of HDAC2-overexpressing M2-like TAMs to cancer cells was significantly correlated with poor overall survival in lung cancer patients." (PMID 39516356, 2024). "HDAC2 was overexpressed in lung cancer tissues compared to adjacent normal tissue." (PMID 36968022, 2023). "FKBP3 which is a member of FK506-binding proteins, could promote proliferation of lung cancer cells through regulating Sp1/HDAC2/p27, we assumed that its immunoregulation effects could be related to HDAC2." (PMID 33648465, 2021). "In fact, overexpression of HDAC2 is observed in lung cancer tissues." (PMID 28099148, 2017). "Increased expression of survivin and HDAC2 are detected in cancer cells including lung cancer." (PMID 25605253, 2015). "Together, these findings suggest that HDAC2 might be an important molecular player in the regulation of Mdm2 and survivin expression levels in lung cancer cells." (PMID 25605253, 2015). "Comparison of HDAC2 and survivin mRNA expression levels between normal and cancer were performed using TissueScan Cancer Array (each containing cDNAs from 8 different normal lung and 40 lung cancer patient tissues)." (PMID 25605253, 2015). "They further suggest that HDAC2 may exert a dominant effect on lung cancer cell survival by sustaining Mdm2-survivin levels." (PMID 25605253, 2015). "In lung cancer, low-dose butyrate enhances tumour growth and metastasis through extracellular matrix remodelling, upregulation of MMP15, and HDAC2-dependent activation of the oncogenic lncRNA H19, which also promotes M2 macrophage polarization." (PMID 40925904, 2025). "For example, a recent study showed that HDAC2, YY1, and c-Myc participate in lung cancer growth and development." (PMID 41009346, 2025). "Earlier DRUGSURV searches found that lung cancer patients with increased HDAC1, HDAC2, and HDAC6 had a poor prognosis." (PMID 40006525, 2025).
lung carcinoma (continued). "The downregulation of CRNDE inhibited lung cancer progression and decreased the migration and invasion of NSCLC cells by decreasing the expression of miR-455–3p, which targeted HDAC2." (PMID 36968022, 2023). "On the other hand, among the co-downregulated transcription factors in lung cancer, we focused on RUNX1, histone deacetylase 2 (HDAC2), and peroxisome proliferator-activated receptor gamma (PPARG)." (PMID 36142846, 2022). "In lung cancer samples, we also observed a significant overexpression of HDAC1, HDAC2, HDAC6 and also DNMT1 and DNMT3A." (PMID 28634396, 2017). "X-radiation and siRNA inhibit expression of HDAC1 and HDAC2, weaken the inhibitory effect of HDAC on Axin, upregulate Axin expression and induce apoptosis of lung cancer cells." (PMID 23110995, 2012). "Clinically, lung cancer patients with high HDAC1, HDAC2, and HDAC6 levels have a poor prognosis." (PMID 40732250, 2025). "Similar results were obtained when the expression of both HDAC1 or HDAC2 was inhibited, suggesting that suppressing HDAC1 and HDAC2 expression both genetically and pharmacologically leads to activation of NKG2D ligands and facilitate NK cell-mediated anti-tumor effects in lung cancer." (PMID 39161385, 2024). "In conclusion, our study highlights the significant role of HDAC2 in TGF-β-induced EMT and suggests that HDAC2 could be a promising therapeutic target for the inhibition of lung cancer cell migration." (PMID 37495623, 2023). "We set out to investigate the co-expression of HDAC1 and HDAC2 in lung cancer cell lines and to use an unbiased siRNA screen to identify DUBs that may regulate HDAC1 and/or HDAC2 expression." (PMID 25970771, 2015). "For example, in a lung cancer (LC) relapse model, butyrate derived from Roseburia inhibited HDAC2, increased H3K27 acetylation at the H19 promoter, and induced M2 macrophage polarization, thereby increasing the expression of H19 in tumor cells and promoting lung cancer metastasis." (PMID 41355959, 2026). "However, it has been thoroughly proven that HDAC2 is overexpressed in tissue samples obtained from patients with lung cancer, with a negative correlation between HDAC2 levels and prognosis." (PMID 37834214, 2023). "Therefore, HDAC1 and HDAC2 play a central role in the transcription of NKG2D ligands, and the specific inhibition of HDAC1 and HDAC2 might be a new strategy for treating lung cancer by promoting NK cell-mediated anticancer immunity." (PMID 34203519, 2021).